MIR218-1 (microRNA 218-1)
Synonyms: hsa-mir-218-1; MIRN218-1; mir-218-1
Gene: MicroRNA gene on chromosome 4 (20,528,275 to 20,528,384, forward strand). Ensembl gene ENSG00000207732.
Gene Ontology:
Biological process: miRNA-mediated post-transcriptional gene silencing
Cellular component: RISC complex
Homologues: Orthologues: chimpanzee ptr-mir-218-1 (100% identical), guinea pig MIR218-1 (100% identical), rabbit MIR218-1 (100% identical), macaque mml-mir-218-1 (99% identical), mouse Mir218-1 (97% identical), tropical clawed frog MIR218-1 (85% identical), pig ssc-mir-218-1 (75% identical). Paralogues in human: MIR218-2 (64% identical).